CD4 (CD4 molecule)
Diseases named in the same sentence as CD4 in open-access papers (continued):
Sharing a sentence is not in itself a finding about the gene and the disease.
AIDS (continued). "Based on the available evidence, the European AIDS clinical society recommends the following: “ART should be started as soon as possible (within 2 weeks of initiating TB treatment) regardless of CD4 count." (PMID 36749231, 2023). "Advanced HIV disease is defined as a CD4 count below 200 cells/mm3 or presenting with an AIDS-defining event, regardless of the CD4 cell count." (PMID 37351535, 2023). "Nearly a fifth of patients did not have HIV virologic suppression (19%), 14% had CD4 counts <200 cells/μL, and 16% met criteria for AIDS." (PMID 38023539, 2023). "Our findings support repeated measure of IL-18 in cART-naïve persons for early identify patients that would not responds to CD4 gains despite virological suppression to prevent clinical progression to AIDs and non-AID events." (PMID 37937297, 2023). "As such, our study has limitations, particularly regarding lack of CD4 count, AIDS status, opportunistic infections, antiretroviral treatment status and COVID-19 status and vaccination." (PMID 37951907, 2023). "In patients with acquired immunodeficiency syndrome (acquired immunodeficiency syndrome, AIDS), it has been found that CD4+CD8+DPT cells can make multiple immune responses to HIV antigens to suppress HIV, which is an essential part of AIDS-specific cellular immune response." (PMID 37377966, 2023). "As AIDS is characterized by a lack of CD4+ T lymphocytes, vaccines targeting common AIDS-related mycoses that work independently of adaptive immunity are of critical importance." (PMID 36993966, 2023). "The late presentation of HIV infection was defined by the European Late Presenter Consensus working group as a patient presenting for care with a CD4 count < 350 cells/μL or presenting with an established AIDS-defining event, regardless of the CD4 cell count." (PMID 36895684, 2023). "The consensus definition of late presenters (LPs) says that these are individuals living with HIV-1 diagnosed with a baseline CD4 count lower than 350 cells/mm3 or with an AIDS-defining event, regardless of CD4 cell count." (PMID 38140659, 2023). "In our models, the presence of the AIDS stage and the current age over 50 years, enhanced by late HIV diagnosis, are postulated as limiting factors in achieving an improvement in absolute CD4, CD8 %CD4, and CD4/CD8 ratio." (PMID 36769822, 2023). "According to available records, people who have been infected with HIV but have not been diagnosed with AIDS (CD4+ T lymphocytes > 200/mL) have no complications, whereas people with AIDS can develop disseminated vaccinia infection after vaccination." (PMID 36769562, 2023). "Chronically SIV-infected African Green Monkeys (AGMs) partially recover mucosal CD4+ T-cells, maintain gut integrity and do not progress to AIDS." (PMID 36813761, 2023). "In African NHPs that are natural hosts of SIV, retroviral infections are nonpathogenic, i.e., animals do not progress to AIDS, despite a very robust viral replication and a massive mucosal CD4+ T-cell depletion during acute infection." (PMID 36813761, 2023). "CMVR was preponderant in white and non-Hispanic, homosexual AIDS individuals with high HIV RNA load or low CD4+ T-cell count." (PMID 37305416, 2023). "One (0.99%) HIV patient on antiretroviral therapy (ART) with normal clusters of differentiation 4 (CD4) count without evidence of AIDS was admitted to the labor room in the first wave of COVID-19 and none in the second wave." (PMID 36938274, 2023). "China has implemented an early treatment policy to all HIV/AIDS patients regardless of CD4 + counts since late 2016." (PMID 38049910, 2023). "When those conditions are met, NHPs do not progress to AIDS, regardless of the degree of CD4+ T-cell depletion and despite a robust viral replication." (PMID 36813761, 2023). "We used a linear regression model to analyze and compare the changes of CD4 in patients without AIDS defining symptoms versus patients with AIDS defining symptoms." (PMID 36584083, 2022).
AIDS (continued). "Human immunodeficiency virus (HIV)/Acquired immunodeficiency syndrome (AIDS) disease progression and antiretroviral therapy (ART) success are monitored by Cluster of Differentiation 4 (CD4) T-cell quantification, clinical criteria and viral load quantification." (PMID 35700178, 2022). "Patient B. In July 2022, a Black man in his 30s with AIDS (CD4 <10 cells/mm3) and not receiving ART developed a rash on his face, head, back, and genitals." (PMID 36327164, 2022). "Therefore, given that the design of clinical trials evaluating the development of non-AIDS comorbidities according to the ART strategy is unlikely, evaluation of the effect of therapies on surrogate markers, such as the CD4/CD8 ratio, is justified." (PMID 35432298, 2022). "Additionally, individuals in the boosted PI group started ART with lower CD4 cell count, higher HIV-RNA viral load and higher proportions of pre-ART AIDS compared to the other two groups." (PMID 36016299, 2022). "For the remaining 30 patients who were not diagnosed by CD4+ count alone, AIDS diagnosis was made based on the presence of one or more AIDS‐related opportunistic infections, regardless of CD4+ count." (PMID 35305282, 2022). "Therefore, the number of CD4 cells and the CD4/CD8 ratio after treatment in HIV/AIDS patients are key factors for successful treatment." (PMID 35646738, 2022). "The rate of having a history of an AIDS diagnosis was significantly lower, and the duration since the HIV-positive diagnosis and the duration of ART were significantly longer in the CD4 ≥ 500 cells (mm3)−1 group than in the CD4 < 500 cells (mm3)−1 group." (PMID 35276785, 2022). "The introduction of highly active antiretroviral therapy (HAART) has led to a reduction in the incidence of TB among patients with AIDS, regardless of CD4+ lymphocyte count at the start of treatment." (PMID 35246066, 2022). "We recommended strengthening Bangladesh’s HIV/AIDS prevention, treatment and management program by evaluating the program effectiveness, with special focus on improvement of the supply chain of ART-related medicines and CD4 tests to slow the HIV transmission." (PMID 36269716, 2022). "Infection with HIV leads to a decrease in CD4+ T cells and ultimately develops into AIDS in patients who do not receive highly active antiretroviral therapy." (PMID 35458449, 2022). "However, in contrast to human AIDS, mice with MAIDS are characterized by lymphoproliferation of CD4+ T and B cells due to a faulty Fas/Fas ligand (Fas L) system as MAIDS progresses." (PMID 35203323, 2022). "People living with HIV/AIDS are enrolled in lifelong Anti-Retroviral Treatment (ART) irrespective of their clinical staging as well as CD4 cell count." (PMID 36249247, 2022). "In people living with HIV/AIDS (PLWHA), initiation of the antiretroviral therapy (ART) lead to sustained effective suppression of viral replication, increasing CD4 + T cell count, reversal of most immunological disturbances, and reduction in risk of morbidity and mortality." (PMID 35114959, 2022). "KV74 also showed a reduction in platelets, a recognized correlate of AIDS in PTM, between 16 and 40 weeks post-infection in combination with low levels of CD4+ T cells comparable to SIVmac239, although platelets in this animal subsequently recovered to baseline." (PMID 35714165, 2022). "Therefore, researchers proposed the concept of functional AIDS cure, that is, long-term control of HIV replication after discontinuation of treatment to maintain the normal number and function of CD4+T cells." (PMID 35211115, 2022). "During the observation period, the subject had steady CD4 T-cell counts, no clinical signs of AIDS, and slightly increased viral load from 2016 to 2020." (PMID 35372102, 2022). "On the one hand, slower CD4+ T cell depletion, slower AIDS progression, higher HIV-1 viral control without antiretroviral treatment, and lower mortality rates have been described in people living with HIV-1." (PMID 36366570, 2022).
AIDS (continued). "Compared with the healthy control group, the proportion of activated CD4+ T cells and CD8+ T cells were significantly higher in the AIDS and pre-AIDS groups, and the proportion of activated CD4+ T cells increased significantly with the severity of the disease (P<0.01)." (PMID 36685491, 2022). "Patient C. In July 2022, a non-Hispanic White man in his 40s with AIDS (CD4 <10 cells/mm3) and not receiving ART was evaluated for a rash on his face, torso, hands, feet, and perianal area; lesion swabs tested positive for MPXV DNA by PCR." (PMID 36327164, 2022). "We hypothesize that in people with AIDS (or PWH and advanced disease), there may be opportunistic infections that affect the white blood cell count, which in turn can affect the CD4 T-cell count value." (PMID 35812431, 2022). "By inducing CD4+ T cell depletion, and as a result mimicking the HIV/AIDS disease state, we could probe the role of CD4+ T cells in the maintenance of granulomatous regions in this model." (PMID 35587201, 2022). "Therefore, it was speculated that derivatives of HIV induced the expression of TLR2 in resting CD4+T cells, thus inducing the acquisition of resting and memory CD4+T cell effector phenotypes and leading to the acceleration of viral replication, immune disorders, and the progression of AIDS." (PMID 35211115, 2022). "However, we rechecked 1,256 patients with CD4+ T cell count at HIV diagnosis and nine deaths from AIDS within one year after the first HIV diagnosis and reclassified 81 specimens as chronic HIV infection." (PMID 35732657, 2022). "Current evidence suggests that low CD4+T-cell counts increase the incidence rate and mortality of cardiovascular diseases and are closely related to the occurrence of AIDS-related or non-related tumors and HIV-related neurocognitive diseases." (PMID 36195585, 2022). "In 2020, 34.2% of the infections were diagnosed late (defined as CD4 < 350 cells/mm3 or AIDS and no indication of a recent infection)." (PMID 36463126, 2022). "In our study, baseline AIDS was a better predictor for BMI gain whereas baseline CD4 cell count and HIV-RNA viral load had no additional statistically significant effect on the rate of BMI increase." (PMID 36016299, 2022). "The CD4+ cell count test, early identification and treatment of AIDS patients, together with co-trimoxazole prevention and treatment programs were important approaches in extending the survival time and reducing the death rates from AIDS-related illnesses." (PMID 35979516, 2022). "Regarding factors associated with mortality, it was consistent with what is previously known that old age, high VL, and low CD4 cell counts increased mortality and supported our results that AIDS-related deaths were more common than non-AIDS-related deaths." (PMID 35353840, 2022). "Lack of information on CD4 cell count or previous AIDS events was an important limitation, as it precluded ascertaining the role of immunodepression in the evolution of COVID-19." (PMID 35561704, 2022). "Elevated anemia in patients with CD4 counts of ≤500 could be due to destruction and diminished production of RBC resulting in low Hgb as HIV advances to AIDS." (PMID 35245289, 2022). "Very late presentation, on the other hand, is defined as diagnosis with lymphocyte CD4+ count lower than 200 cells/μL or, regardless of the lymphocyte count, presentation with an AIDS-defining event." (PMID 35457436, 2022). "Additional infectious workup on Day 40 of hospitalization revealed a new diagnosis of AIDS (positive HIV-1 antibody, CD4 count 111 cells/mm3; HIV-RNA 326,000 copies/mL) and presumed late latent syphilis (positive anti-treponemal antibody, negative RPR, positive TPPA)." (PMID 35148782, 2022). "However, other studies have reported similar effects for low CD4 cell count and/or high HIV-RNA viral load instead or on top of AIDS at baseline." (PMID 36016299, 2022).
AIDS (continued). "In bivariate regression analysis marital status, living condition, lost job, HIV related stigma, social support, CD4 count, side effect to HAART, WHO HIV/AIDS clinical stage, drug regimen and medication adherence were associated with depression at p-value = < 0.25." (PMID 35986352, 2022). "LP are patients newly diagnosed with a baseline CD4 count lower than 350 cells/mm3 or with an AIDS-defining event, regardless of CD4 cell count." (PMID 35495657, 2022). "Therefore, in order to maximize CD4 count and improve survival, the HIV/AIDS chronic care package must place a strong emphasis on these predictors for early screening, prevention, early detection, and treatment of such predictors." (PMID 36172060, 2022). "According to the CD4+ T-cell counts, ART-treated males with AIDS were divided into two groups: those with CD4+ T-cell counts < 350 cells/μL (moderate or severe reduction of immune function) and those with CD4+ T-cell counts ≥ 350 cells/μL (normal or slightly decreased immune function)." (PMID 36292106, 2022). "We compared their rates of CD4 recovery to patients with Acquired Immunodeficiency Syndrome (AIDS) without opportunistic infections (CD4 cell count < 200/μL—7 patients)." (PMID 36298842, 2022). "First, the definition of LP in our study included only CD4 cell count at ART initiation ≤ 350 cells/μL and not AIDS-defining events as we focused in CD4 responses." (PMID 35958520, 2022). "CD4+ T-cell counts play an important role in treatment decisions and clinical management for patients with HIV/AIDS, especially for patients in places with limited resources and those who present late for care and in treatment monitoring where viral load monitoring is restricted." (PMID 34326884, 2021). "Hence, it is worth investigating the hospital-level CD4 cell count data, especially from hospitals that stock long-term series data covering a large group of patients with HIV/AIDS." (PMID 34511561, 2021). "Accordingly, number of CD4 lymphocytes (CD4) in HIV-infected individuals is a principal indicator of HIV progression and death from AIDS and that lower CD4 cell count level indicates that the immune system may be compromised." (PMID 33766121, 2021). "More than two-thirds (64.9%) did not have prior AIDS diagnosis, and 46.9% had CD4 ≤200 cells/mm3 at the time of HIV diagnosis." (PMID 34077481, 2021). "Late presentation (LP) was defined as the presence of either an AIDS-related condition regardless of CD4 cell count or a CD4 count of < 350 cells/mm3 at presentation for care." (PMID 34742286, 2021). "This is the first large-scale population-based epidemiological study using CD4 cell count data and could aid in understanding the HIV/AIDS epidemic in Japan." (PMID 34511561, 2021). "In both asymptomatic subjects and those positive for AIDS-KS, the TTV level was significantly elevated in parallel to the concentration of HIV in the circulation and significantly reduced as the concentration of CD4+ lymphocytes increased in the circulation." (PMID 35096897, 2021). "Since 2019, taking of ARTs is systematic in HIV/AIDS patients regardless of the clinical status and CD4+ level." (PMID 34257647, 2021). "The low incidence of cHL in AIDS patients with low CD4+ T-cell counts and the increased frequency of this lymphoma in HIV+ patients under anti-retroviral therapy with normalized CD4+ T-cell counts also argue for an important role of CD4+ T cells in HL pathogenesis." (PMID 33686198, 2021). "The incidence, in patients with CD4 counts of less than 50/mm3, can be as high as 10 per 100 patients-years in French Guiana, making it the first opportunistic infection in HIV patients at the AIDS stage." (PMID 34072190, 2021). "In the absence of treatment, viral replication resumes, new CD4+ cells are infected, and infected individuals progress to develop acquired immunodeficiency syndrome (AIDS)." (PMID 34578455, 2021).
AIDS (continued). "In order to improve the quality of life of PLWH, over the last four years, hospitals specializing in the treatment of AIDS have been gradually implementing surgical interventions for PLWH who have not been under HAART (or for whom ART has failed) and in those with CD4-CC < 200 cells/μl." (PMID 34616598, 2021). "It has been shown that HIV-related factors, such as low CD4+ cell count and prior history of AIDS, are no longer predictive of worse survival outcome in the cART era 32, 33, consistent with our results." (PMID 33854591, 2021). "However, at first clinical visit, fourfold more men were in WHO stage III/IV AIDS than women (9.8% vs 2.4%; p<0.0001), and 20.6% of men and 11.4% of women had advanced HIV disease with CD4 <100 cells per μL (p = 0.001)." (PMID 33577559, 2021). "All newly diagnosed HIV-infected patients should initiate cART, regardless of CD4+ T cell count, to decrease the risk of HIV transmission and prevent the progression of AIDS and the occurrence of AIDS-related events." (PMID 35115928, 2021). "Other studies have also recently shown that higher increases in CD4+ T-cell count during the first years of ART or initiating ART with lower CD4+ T-cell counts, and not necessarily AIDS, were associated with HBsAg-seroclearance." (PMID 34372547, 2021). "Among persons with no clinical AIDS, those with CD4 count ≥ 200/mm3 started ART later in comparison to persons with CD4 count < 200/mm3." (PMID 34006927, 2021). "Our findings conclude that cryptococcal meningitis occurs in most instances in long-standing HIV and cases of noncompliance with therapeutic orders for AIDS, when severely decreased CD4 levels allow most opportunistic infections to develop." (PMID 35054221, 2021). "This difference may indicate that male and rural patients with CD4-CC < 200 cells/μl have a lower willingness to seek medical care, leading to late detection of HIV/AIDS or decreased adherence to ART treatment." (PMID 34616598, 2021). "These people are considered “immunological non-responders,” that is, HIV-infected individuals who fail to achieve normalization of CD4+ T-cell counts despite persistent virological suppression, which leads to AIDS and non-AIDS comorbidities." (PMID 34504234, 2021). "Unfortunately, this work did not consider HIV infection severity, AIDS status or CD4 count, and viral load." (PMID 34372902, 2021). "The results showed that CD4+ T cell count (z = -4.093, P < 0.0001), CD8+ T cell count (z = -3.780, P = 0.001), WBC (t = -2.538, P = 0.016), and neutrophil (t = -2.322, P = 0.026) were significantly increased in AIDS patients after nutritional intervention." (PMID 35003070, 2021). "The T-cell counts were significantly reduced in COVID-19 patients—the surviving T cells in severe COVID-19 patients with CD4 T-cell counts were lower than 400 cells/μl —but which were still higher than those of patients with HIV/AIDS in this study (226 cells/μl)." (PMID 34646783, 2021). "Those included were more likely to be White, gbMSM, diagnosed between 2000 and 2003, with a higher CD4 cell count, without an AIDS diagnosis and a slightly lower viral load." (PMID 33577551, 2021). "An important component and determinant of HIV infections involves not only CD4 count but also viral load and access and adherence to ARV therapy, which remains an essential aspect of long-term outcomes, including progression to AIDS and survival among HIV patients." (PMID 33737527, 2021). "We still need to know whether there are any differences between controlled HIV infection with undetectable viral load and a CD4 count ≥200 cells/μl and uncontrolled HIV infection or AIDS in COVID‐19 outcomes." (PMID 34324280, 2021). "Thus, both CD4 T-cell counts and plasma HIV RNA are important prognostic markers of progression to AIDS and serve as main indicators for initiation of antiretroviral therapy." (PMID 34399785, 2021).